L1CAM (L1 cell adhesion molecule)
Diseases named in the same sentence as L1CAM in open-access papers (continued):
Sharing a sentence is not in itself a finding about the gene and the disease.
tumor (continued). "Elevated lactate in the tumor microenvironment disrupts mitochondrial function, promotes histone lactylation, and enhances reactive oxygen species (ROS) production, which collectively contribute to the upregulation of oncogenic proteins such as L1CAM and ultimately accelerate tumor progression." (PMID 41551444, 2026). "This means that L1CAM could help pathologists more accurately identify this rare tumor type." (PMID 40805143, 2025). "However, L1CAM staining was unrelated to tumor phenotype in seven other tumor entities." (PMID 41328908, 2025). "L1CAM tumor expression was associated with the risk of distant but not vaginal recurrence." (PMID 40870967, 2025). "L1CAM, a cell adhesion molecule, might influence tumor invasion and metastasis." (PMID 37702857, 2023). "Finally, we could show that L1CAM depletion decreases viability and tumor growth of etoposide‐resistant RB cell lines upon etoposide treatment in vitro and in vivo." (PMID 34228897, 2022). "Furthermore, we discovered that L1CAM was linked to immune cell infiltration and ICG (CD274, LAG3, PDCD1LG2, CTLA4), and we hypothesized that L1CAM may have a regulatory role in the tumor microenvironment, influencing tumor growth and metastasis." (PMID 36212450, 2022). "Furthermore, the adhesion molecule L1CAM (CD171) is upregulated in pancreatic duct epithelium during the progression of PDAC and is associated with the accumulation of immunosuppressive T cells in tumor stroma." (PMID 35965504, 2022). "In those patients, characterized by an “early-relapsing” disease after platinum-based treatment, the combination of L1CAM MAbs with chemotherapy might be explored, following the rationale of tumor cell resensitization to standard chemotherapy mediated by L1CAM inactivation." (PMID 36358847, 2022). "In addition, the observation that L1CAM promotes the enrichment of immunosuppressive T cells within the tumour, contributing to immune evasion and suppression, supports the rationale of the combination between L1CAM blockade and immunotherapy as a strategy to overcome tumour immune escape." (PMID 35429348, 2022). "Moreover, L1CAM expression may be a predictive biomarker for treatment with human monoclonal antibody to resensitize tumour cells to platinum‐based chemotherapy." (PMID 35429348, 2022). "Importantly, like L1CAM overexpression, the loss of PTEN leads to the activation of the AKT pathway, indicating that the same signaling pathway is responsible for an increase in multicellular tumor spheroid formation and metastasis." (PMID 36509990, 2022). "Different ratios (1:1, 5:1 and 10:1) were tested for this experiment because we hypothesized that the previously applied E:T of 1:5 might be unfavorable for the untransduced T cells, which, contrary to CAR T cells, cannot eradicate tumor cells via L1CAM antigen recognition." (PMID 34771652, 2021). "Therefore, we cautiously hypothesise that the opposite responses of L1CAM in tumour cells and normal ECs may be due to the dual nature of Myc (i.e., checkpoint signalling activation and survival in cancer cells vs. genomic instability in normal cells)." (PMID 34078883, 2021). "However, the differential function of L1CAM in tumour and normal cells remains undefined." (PMID 34078883, 2021).
tumor (continued). "Consequently, L1CAM did not improve current risk stratification when adding additional parameters such as tumour grade, age, histology, LVSI, or ER and PR status." (PMID 34659530, 2021). "Thus, STAT3 blockade inhibited both L1CAM-dependent tumor initiation and growth." (PMID 34645505, 2021). "Furthermore, tumor derived from PDOx_SC exhibited co-expression of L1CAM and NODAL or pSMAD2, suggesting again that L1CAM expression may be functionally linked to NODAL signaling." (PMID 33897875, 2021). "For instance, an upregulation of the adhesion molecule L1CAM (CD171) by several PDAC cells is associated with an epithelial mesenchymal transition and an upregulation of mesenchymal protein vimentin, which correlates with a higher tumor grade, and can influence Treg migration." (PMID 32384638, 2020). "Besides these strategies for functional inactivation, the expression pattern of L1CAM in cancer suggests that anti-L1CAM antibodies may also be harnessed to deliver cytotoxic agents to tumor cells." (PMID 32429448, 2020). "Also, the roles of L1CAM interaction with ephrins, and potential downstream migration guidance regulation in tumors and the occurrence and metabolic function of transmembrane-containing cleavage forms in mitochondria in tumor cells await further investigation." (PMID 31455004, 2019). "L1CAM-integrin interactions can control interaction of tumor cells with other cell types, including endothelia, mesothelia, nerves, and cancer-associated fibroblasts, allowing for heterotypic cell adhesions that could potentially promote tissue invasion and intravasation into the vasculature." (PMID 31455004, 2019). "Additionally, the adhesion molecule L1CAM (CD171) is upregulated in the pancreatic ductal epithelium during PDAC progression, in association with the accumulation of immunosuppressive T cells in tumor stroma." (PMID 30764482, 2019). "Thus, the expression of CHL1, NrCAM, L1CAM, and ALCAM may be associated with a less aggressive tumor and, as a consequence, with a better prognosis." (PMID 31989042, 2019). "In addition to the central nervous system, highly glycosylated IgSF-CAM members also play critical roles in other systems affected in CDG patients, such as the developing eyes and immune system with ICAM1, or in other diseases like cancer, where L1CAM plays a critical role in tumor metastasis." (PMID 30311906, 2018). "Thus, it is tempting to speculate that the regulation of β3 integrin expression contributes significantly to the multiple roles of L1CAM in tumor vasculature." (PMID 28134764, 2017). "Thus, tumour growth induced by Mint3/L1CAM in fibroblasts might localize at the border between cancer and stromal cells." (PMID 28504692, 2017). "This phenomenon may be responsible for accelerated tumor dissemination in L1CAM-positive tumors." (PMID 27832351, 2017). "Therefore, it may be likely that Ab417 exerted tumor growth inhibition in vivo by inducing down-regulation of L1CAM on the cell surface and thereby resulting in reduced tumor cell proliferation by a cytostatic effect." (PMID 28166242, 2017). "Finally, several studies have reported the aberrant expression of L1CAM in different tumor types." (PMID 28134764, 2017). "Overall, L1CAM might be an effective poor prognostic factor for patients with various tumour types." (PMID 27833079, 2016). "However, on the transcriptome level we were not able to confirm the association between the levels of tumor L1CAM mRNA and the magnitude of residual disease after radical surgery." (PMID 27174921, 2016). "Moreover, L1CAM expression in tumor cells conferred the capacity to form metastases." (PMID 24422715, 2013). "The statistically significant impact of L1CAM expression for overall survival (P = 0.008) was more significant than the tumor stage (P = 0.009) that is widely used at present, suggesting that L1CAM expression could be a useful marker to predict patient survival." (PMID 22888955, 2012).
tumor (continued). "Therefore, we aimed to determine whether overexpression of one of the L1CAM isoforms specifically enhanced the invasive potential of a tumour cell line." (PMID 21541352, 2011). "Overexpression of neither L1CAM variant influenced tumour cell proliferation." (PMID 21541352, 2011). "Thus, by interacting with the ECM and/or stroma cells, tumor cells become highly protected from apoptosis induction involving alterations in the expression of adhesion molecules such as L1CAM or integrins, or elevated secretion of cytokines (TGF-β) and chemokines." (PMID 21914164, 2011). "We previously reported that TGF-β1 downregulates L1CAM expression in PDAC, leading to a more aggressive tumor phenotype." (PMID 40770187, 2025). "This study systematically analyzes the distribution of EMT subtypes of CTCs and their L1CAM positivity profiles in patients with ESIBC, revealing a close relationship between phenotypic heterogeneity of CTCs and tumor biological behavior." (PMID 41306535, 2025). "The interplay of EGFR, L1CAM, MAPK, and DAP12 signaling pathways is crucial in TN BC, as their activation can drive tumor proliferation, invasion, and resistance to therapy in this aggressive subtype." (PMID 40894036, 2025). "L1CAM facilitated the movement and accumulation of immune-suppressing T cells (T-regs) and a unique subset of CD4+CD25 CD69+ T cells within the tumor’s microenvironment." (PMID 40699746, 2025). "The cell adhesion molecule L1CAM (CD171, in short L1) is upregulated in many human cancers, enhancing tumor cell migration." (PMID 38732030, 2024). "Again, co-expression of L1CAM and LINC01187 within the same tumor cell was a very rare event observed in HOT." (PMID 37994665, 2024). "In vivo, we also observed a significant reversal of increased tumor growth and cervical LN metastasis in ADAMTS1-overexpressed HSC-3 cells when these cells were engineered to express shRNA targeting L1CAM or EGFR." (PMID 38263290, 2024). "L1CAM short spacer-CD28/ζ CAR T cells expanded and induced initial tumor regression more than the long spacer at the tumor site in the face of the cancerous target." (PMID 38178096, 2024). "Immunohistochemistry was performed on formalin-fixed paraffin-embedded (FFPE) tumor tissue samples to assess the expression of CSC markers (CD133, CD44, and L1CAM) and immune checkpoint inhibitor marker (PD-L1)." (PMID 39148690, 2024). "Dual staining of principal cell marker L1CAM and intercalated cell markers LINC01187/FOXI1 confirmed that L1CAM and LINC01187/FOXI1 were expressed in a mutually exclusive pattern in most tumor cells in HOT." (PMID 37994665, 2024). "ADAMTS1 acts as a tumor metastasis promoter in OSCC, and L1CAM and EGFR are critical determinants regulated by ADAMTS1 when executing its prometastatic effect via EMT induction." (PMID 38263290, 2024). "The L1 cell adhesion molecule (L1CAM) plays important roles in the development and plasticity of the nervous system as well as in tumor formation, progression, and metastasis." (PMID 37239955, 2023). "Using L1CAM-specific CAR-T cells, the short spacer-CD28/ζ CAR design showed maximum expansion at the tumor site and initiated tumor regression in mouse xenograft models." (PMID 38516299, 2023). "This suggestion can be also supported by a study that demonstrated the over-expression of L1CAM promoted invasion and migration of TNBC cells, and L1CAM was therefore regarded as a driver of tumour progression." (PMID 36347335, 2023). "In recent studies, it has been discovered that certain tumor types show a high level of expression of neuron receptors such as Trks, NGFR, GFRα, L1CAM, NCAM, AchRs, AMPARs, NMDAR, and dopamine receptors." (PMID 37566075, 2023). "Based on the expression levels of four proteins: CETP, HGFL, L1CAM, and LAIR2, combined with tumor diameter, serum AFP, and GGT concentrations to establish a preoperative MVI status prediction model for HCC patients." (PMID 38049860, 2023).
tumor (continued). "We have previously shown that Lgr5 high/wnt high/L1CAM low and Lgr5 low/wnt low/L1CAM high cells have distinct roles with the former being important for homeostasis and sporadic CRC tumor initiation and the latter for regeneration and metastasis." (PMID 36611031, 2023). "The findings imply that the genes CHRM2, GRIN1, L1CAM, and SEMA4F in EC have pro- or oncogenic effects as a result of the combined activity of several signaling pathways influencing tumor growth." (PMID 36212450, 2022). "Alternatively, genetic depletion of L1CAM, serpin B1, ARP2/-3, RUNX1, or ITGA5 in tumor cells has been demonstrated to attenuate vessel co-option." (PMID 35951441, 2022). "In this subset, we evaluated the predictive performance of a model considering L1CAM as well as FIGO stage and tumour grade." (PMID 35429348, 2022). "However, whether L1CAM plays a role in early tumor development is unknown." (PMID 36509990, 2022). "It targets Notch1, L1CAM, MMSET and thus inhibits EC cells migration, invasion, and EMT in vitro as well as tumor growth in vivo." (PMID 36335210, 2022). "Our group developed CAR T cells targeting the glycosylated CE7 epitope of L1CAM (formerly CD171), which is specifically expressed on tumor cells." (PMID 34771652, 2021). "The bioluminescence increase was also delayed by 1 week compared to L1CAM-SS-28/ζ CAR T cells, indicating less efficient CAR T cell homing or expansion at the tumor site." (PMID 33801448, 2021). "In conclusion, L1CAM promotes tumorigenesis and induces CCL22 secretion in ESCC tumor cells via PI3K/Akt and NF-κB." (PMID 33710805, 2021). "Tumor initiation is a defining property of CSC and, therefore, we determined the impact of L1CAM on the tumor-initiating potential of OC cells." (PMID 34645505, 2021). "Tumor cell encounter in the bioprinted 3D tumor model induced release of lower levels of the cytokine, interferon gamma (IFNG), from L1CAM-CAR T cells than encounter in 2D cocultures (SS-BB/ζ: p=0.07; LS-BB/ζ: p=0.06)." (PMID 34267756, 2021). "The function of L1CAM may be required in the most proliferative components with ambiguous differentiation in ELTMDs, and its expression may be lost along with mesenchymal, glioneuronal, and ependymal (in the recurrent tumor of case 2) differentiation with lower proliferative activity." (PMID 33576087, 2021). "L1CAM KD PDO#2 cells showed a reduced proliferative capacity compared to the sh scramble control, and delayed tumor growth when subcutaneously injected in nude mice." (PMID 33897875, 2021). "L1CAM-specific CAR T cells more easily killed tumor cells in 2D cocultures (SS-BB/ζ L1CAM-CAR T cells lysed: 95.9 ± 0.8% in 2D, 39.9 ± 27.1% in 3D; LS-BB/ζ L1CAM-CAR T cells lysed: 92.1 ± 3.6% in 2D and 42.4 ± 22.0% in 3D)." (PMID 34267756, 2021). "L1CAM-LS-28/ζ CAR T cells produced a mixed response, since bioluminescence at the tumor site increased only in some mice." (PMID 33801448, 2021). "The effects of the L1CAM, CXCR4 and NODAL on tumor growth, proliferation, migration, invasion, colony-formation ability, metastasis and chemoresistance were investigated both in vitro and in vivo." (PMID 33897875, 2021). "After only 12 hours, 63,604 LS-BB/ζ L1CAM-CAR T cells, 40,658 SS-BB/ζ L1CAM-CAR T cells and 33,523 untransduced T cells had infiltrated the 3D tumor model." (PMID 34267756, 2021). "Although both murine L1CAM-specific CAR T cells with CD28 co-stimulus produced similar levels of cytokines upon stimulation in vitro, anti-tumor activity in vivo differed." (PMID 33801448, 2021). "Tumor-initiating capacity of SKOV3ip and IGROV1 cells sorted by FACS for L1CAM and CD133 (500, 1000 and 3500) was assessed in CD1 nude mice." (PMID 31952346, 2020). "We found that L1CAM, vimentin and TGF-β1 expression has a strong tendency toward co-occurrence in tumor tissues, and high expression of this gene signature is associated with reduced overall survival." (PMID 31952346, 2020).
tumor (continued). "Expression levels of many proteins were altered with resistance development including gp100/PMEL, CD171/L1CAM, GAB2, mTOR and PI3K-p85 which have been previously shown to be upregulated in tumors including CMM and promoting tumor progression." (PMID 33082316, 2020). "We showed that L1CAM decreases stemness, EMT and subsequently their dissemination, supporting its functional role as tumour suppressor in fully established PDAC." (PMID 32291413, 2020). "Over-expression of L1CAM not only induced NF-κB activation but also mediated the phosphorylation of FAK and Src, which promoted cancer cell proliferation and tumor growth." (PMID 32047513, 2019). "The strongest upregulation was a 2.3 log2-fold increase in L1 cell adhesion molecule (L1CAM), a transmembrane glycoprotein of the Ig superfamily that has been shown to promote tumour cell invasion and motility." (PMID 30858446, 2019). "L1CAM knockdown led to a decrease in in vitro proliferation for MV3, but obviously even increased tumor growth in vivo." (PMID 29432466, 2018). "When we correlated the expression of L1CAM in EC with DFS, we found that higher expression of L1CAM was present in tumor patients with lower disease free survival (5y-DFS 26.1% vs 60.7%, p = 0.002)." (PMID 29980240, 2018). "We found that the expression levels of two upregulated genes (L1CAM and FBN1) were also increased along with tumor grade and that the expression levels of four downregulated genes (AUTS2, MAPT, AGT and USH1C) were decreased along with tumor grade." (PMID 29215599, 2017). "Induced L1CAM in fibroblasts activated the ERK signalling via integrin α5β1 in cancer cells, resulting in cancer cell proliferation and tumour growth." (PMID 28504692, 2017). "In our previous study, down-regulation of cell surface L1CAM expression in ICC cells resulted in reduced tumor cell proliferation as well as AKT and FAK signaling in vitro and tumor growth in vivo." (PMID 28166242, 2017). "With regards to the clinical analysis of ccRCC samples from microarrays of GSE66272 and GSE73731, the upregulation of L1CAM and FBN1 and downregulation of AUTS2, MAPT, AGT and USH1C were observed along with an increase in tumor grade." (PMID 29215599, 2017). "Down-regulation of L1CAM expression was shown to reduce proliferation and migration of ICC cells in vitro and tumor growth in vivo." (PMID 28166242, 2017). "We found that the L1CAM, TSPAN3 and SERPINA3 gene expression were significantly up-regulated in M than Wt sporadic tumor samples, whereas COL1A1 and MAT2A mRNA showed similar levels in both groups." (PMID 28418912, 2017). "L1CAM (CD171), a cell surface molecule, is preferentially expressed on GSCs and contributes to tumor growth and survival." (PMID 29246031, 2017). "Selected miRNAs have a role in tumor progression, as e.g., miR-503 directly targets L1 adhesion molecule (L1CAM) and E2F transcription factor 3 (E2F3) mRNAs involved in tumor progression." (PMID 28289479, 2017). "ADAM10 can also generate soluble L1 cell adhesion molecule (L1CAM), which stimulates the migration of tumor cells through binding to the αvβ5 integrin." (PMID 28260841, 2017). "The L1 cell adhesion molecule (L1CAM) extensively participates in nervous system development and the malignant progression of human tumours." (PMID 27833079, 2016). "Our current findings show that L1CAM expression is exclusively found in areas with EMT-like growth (at the invasive border), or in tumours with predominant spray patterned growth, suggesting an association between EMT and L1CAM." (PMID 27028855, 2016).